CD4 (CD4 molecule)
Diseases named in the same sentence as CD4 in open-access papers (continued):
Sharing a sentence is not in itself a finding about the gene and the disease.
uveitis (121 papers, 2009 to 2025). An inflammatory process affecting a part of or the entire uvea. "IL-17A secretion by CD4+ T cells have also been shown to be associated with active uveitis in patients with VKH or Behçet’s disease." (PMID 40433375, 2025). "In patients with Mtb associated uveitis vitrectomy samples have identified CD4+ T cells expressing IL-17 and IFN-γ." (PMID 35921962, 2022). "IFN-γ is one of the major cytokines released by CD4+ Th1/Th17 cells to activate inflammatory cascades and cause local tissue damage in uveitis." (PMID 34869347, 2021). "To decouple the effect of age and disease, we used a linear regression model and found that the increased proportion of CD4+ TM cells was independently associated with uveitis (p = 0.02)." (PMID 30429855, 2018). "Evidence for this coexistence was provided with the fact that both diseases cause uveitis and sacroiliitis, with the predominance of CD4+ T-lymphocytes and the presence of common agents (like Propionibacterium acnes) that are controversial in the pathogenesis." (PMID 24741443, 2014). "The present study showed that the production of IL-17 by stimulated CD4+ T cells, which is associated with active ocular inflammation in BD patients, is significantly elevated in BD patients with active uveitis." (PMID 22546542, 2012). "Several studies show that Th17 cells or IL-17 are associated with ocular inflammatory diseases such as uveitis and CD4+ T cells are capable of producing IL-17." (PMID 22219644, 2011). "The use of cidofovir could stimulate the immune system and thus increase the number of CD4+ T cells, causing ocular inflammation and leading to uveitis." (PMID 36851658, 2023). "To examine whether downregulation of S1pr1 under conditions of LXA4 deficiency can be detected in uveitis-relevant T cells, we assessed S1pr1 expression in CD4+ T cells from inguinal lymph nodes of EAU-challenged Alox5-/- and WT mice by RT-PCR." (PMID 32118582, 2020). "Since DCs play a key role in uveitis by presenting antigens to CD4+ T cells, the effect of sCD83 on T cells could be caused by DCs tolerance." (PMID 30050530, 2018). "Ocular inflammation is a hallmark of all forms of uveitis and one may speculate that this inflammation could be one of contributing factors of diminished CD4+ Teff responses in subjects with IOTB." (PMID 30218032, 2018). "HIV can replicate within the eye causing uveitis, and a low CD4 count is a risk factor for immune recovery uveitis (IRU) which could arise in patients with a history of cytomegalovirus (CMV) infection and could potentially cause subclinical endothelial damage." (PMID 23460854, 2013). "Previous studies found the dysregulations of TBX21/GATA3 and Rorc/Foxp3 ratios in uveitis patients with neuro-BD20, suggesting that a dysregulated function of these T cell subsets may lead to immune imbalance, proliferation and activation of pathogenic CD4+ T cells subsequently leading to uveitis." (PMID 25873156, 2015). "As the key pathogenesis of uveitis is the immunoinflammatory response mediated by CD4+ T cells, we further analyzed the infiltrating cells and found that the frequency of intraocular CD4+ T cells was decreased by DNase I or anti-Ly6G treatment." (PMID 39846254, 2025). "In adoptive transfer EAU, the pathogenic T cell threshold can be extremely low: as few as 40 activated IRBP-specific CD4+ T cells can precipitate uveitis in Lewis rats, whereas on the order of 103-104 cells are typically required to induce disease in mice." (PMID 41394857, 2025). "This can be noted by the marked association of uveitis with HLA-B27-associated systemic diagnoses, uveitis following the reactivation of latent infections, and uveitis following abrupt CD4 + cell count recovery." (PMID 41186895, 2025). "Our proof-of-concept study demonstrates that blocking IL-7 or IL-15 leads to specific depletion of the uveitogenic memory CD4+ T cells and disruption of disease chronicity in uveitis." (PMID 40323267, 2025).
uveitis (continued). "The present study validates the idea from a genetic perspective that CD3 on CM CD4+ T cell and CD3 on CD45RA- CD4+T cell is associated with an increased risk of uveitis." (PMID 39044820, 2024). "While standard MR analysis identified elevated CD3 levels in CM CD4+ T cells and CD45RA- CD4+ T cells as risk factors for uveitis, reverse MR analysis confirmed this causal relationship with slightly varying odds ratios and confidence intervals." (PMID 39144656, 2024). "We then focused on T cells recognizing the P2 epitope of IRBP, as these cells were previously found to be more abundant in mice with uveitis than CD4 T cells recognizing the other two known epitopes of IRBP in C57BL/6 mice." (PMID 38261611, 2024). "Our research indicates that an increased CD3 on CM CD4+ T cells and CD3 on CD45RA− CD4+ T cells percentage is associated with an increased risk of uveitis." (PMID 39144656, 2024). "As a cell adhesion molecule within cells, the intraocular fluid of uveitis patients exhibited a higher percentage of CD4+ and CD8+ lymphocytes due to ICAM-1, in comparison to the control group." (PMID 39839649, 2024). "Previously, we found that approximately 50% of AireGW/+Lyn−/− mice develop uveitis and that disease correlated strongly with a CD4 T cell response to the Aire-regulated retinal protein IRBP." (PMID 38261611, 2024). "In uveitis, autoantigenic T-cells breach the blood-retina barrier, activating antigen-presenting cells and triggering an invasion of macrophages, CD4-positive (CD4+) T-cells, neutrophils, and CD8-positive (CD8+) T-cells." (PMID 39497001, 2024). "In mice with uveitis, ~12% of the CD4 T cells infiltrating the retina bound to the P2/I-Ab tetramer, whereas CD4SP thymocytes bound tetramer with a much lower frequency that was nonetheless elevated compared to non-transgenic thymocytes." (PMID 38261611, 2024). "CD3 levels on CD45RA− CD4+ T cells (OR = 1.087, 95%CI = 1.029 ~ 1.147, p = 0.003) and CD3 levels on CM CD4+ T cells (OR = 1.086, 95%CI = 1.033 ~ 1.141, p = 0.001) were found to be elevated in cases of uveitis." (PMID 39144656, 2024). "CD4+ T cells, including regulatory (Treg) and effector (such as T helper (Th)-1 and Th17 cells), play a crucial role in the development of uveitis and its well-known animal model, experimental autoimmune uveitis." (PMID 39144656, 2024). "Correspondingly, VKHD uveitis demonstrated a selective expansion of CD4+ T cell clones which were enriched in pro‐inflammatory Granzyme H+ CD4+ Tem cluster and showed TCR and Th1 pathway activation." (PMID 37720629, 2023). "Altogether, the different CD4+ and CD8+ T cell composition in uveitis tissue infiltrates are largely driven by effector memory populations, suggesting the effector function of CD4+ and CD8+ T cells preferentially activated in VKHD and BD respectively." (PMID 37720629, 2023). "The average CD4+ T-cell count of patients with uveitis was 433.2 ± 535.6 cells/μL, implying an unsatisfactory immune status." (PMID 38133300, 2023). "In contrast, uveitis in the BD patient had few of these effector CD4+ T cells but was characterised by clonally expanded effector CD8+ T cells expressing CCL5, GZMA, GZMB and PRF1." (PMID 37720629, 2023). "In the absence of active cytomegalovirus (CMV) retinitis and a surge in CD4 count of more than 100 cells/μL over four months, he was diagnosed as a case of immune recovery uveitis (IRU)." (PMID 38022310, 2023). "This difference suggests a potentially different role of CD4+vs. CD8+ T cells in driving uveitis in VKHD and BD." (PMID 37720629, 2023). "The mean CD4+ T-cell count for patients with uveitis and CMV retinitis was 433.2 ± 535.6 cells/μL and 585.0 ± 734.3 cells/μL, respectively." (PMID 38133300, 2023). "Uveitis in VKHD patients showed the dominant role of clonally expanded Th1‐like effector CD4+ T cells expressing IFNG and TNF." (PMID 37720629, 2023).
uveitis (continued). "Another multicenter, prospective study confirmed that vitreous CD4/CD8 or CD4 + measurements are higher in ocular sarcoidosis than in other uveitis etiologies." (PMID 37721575, 2023). "To date, discoveries of adaptive immune mechanisms in uveitis using this model have led to therapies that target T cells, such as CD4+ effector T cells polarized to the Th17 phenotype, a driving pathogenic mechanism of EAU." (PMID 35313917, 2022). "CD4+ effector T cells (TC), especially T helper (Th)-1 and Th17 cells are thought to be critical participants in uveitis pathogenesis." (PMID 39872747, 2022). "EAU is mediated predominantly by CD4+ T- lymphocytes and proinflammatory cytokines, which are similar to the inflammatory profile in naturally occurring uveitis in humans and horses." (PMID 35980983, 2022). "In animal experiments, adoptive transfer of autoreactive CD4+ T cells can induce uveitis in naïve mice." (PMID 39872747, 2022). "Reconstituted Rag1−/− recipients were immunized with IRBP1–20 and the ability of Nlrp12−/− vs. WT CD4+ T cells to expand and trigger uveitis was evaluated." (PMID 35313917, 2022). "Recurrent uveitis in horses develops following primary uveitis when disruption to the blood-ocular barrier occurs, allowing CD4+ T-lymphocytes to enter and remain in the eye." (PMID 35980983, 2022). "At cellular level, there is considerable evidence that CD4+ T cell-dependent immune responses are important in the pathogenesis of uveitis." (PMID 34869347, 2021). "The current core concept on uveitis pathogenesis is represented by the role played by Th CD4 + cells." (PMID 33634341, 2021). "Treg (CD4+CD25hi or CD4+FoxP3+) have been shown to play an important role in protecting against Vogt-Koyanagi-Harada (VKH), ocular BD, JIA-associated uveitis and other NIUs by functionally suppressing Th1 and Th17 cells." (PMID 34502490, 2021). "The present study aimed to review the function and roles of plastic CD4+ T cell subsets in uveitis patients." (PMID 34502490, 2021). "Inflammation in uveitis activates interferon γ, which in turn induces HLA class II, which in turn induces an immune response by presenting antigens to CD4 of T cell." (PMID 34963463, 2021). "Uveitis presents high levels of TNF-α in intraocular fluids which is directly proportional to CD4 + Th cells activation, leading to potentially irreversible tissue damage." (PMID 33634341, 2021). "In this study, we generated mice with targeted deletion of irf4 in the CD4 T cell compartment and show that loss of IRF4 in CD4+ T cells conferred resistance to uveitis." (PMID 33803441, 2021). "As with Nod2-mediated uveitis, the exacerbated pinealitis involved increased CD4+ T cells and CD4:CD8 ratio; thereby supporting an antigen-specific response by which Nod2 controls uveitis." (PMID 33106495, 2020). "As a result, cultured iPS-RPE cells inhibited cell proliferation and the production of IFN-γ by activated uveitis CD4+ T cells, especially Th1-type T cells." (PMID 32899567, 2020). "Similar to peripherally-derived CD4+ T cells, Nod2−/− thymocytes elicited a more severe uveitis compared to WT thymocytes, and recapitulated the T cell-intrinsic signature of augmented IL-17 production to IRBP-stimulation in vitro." (PMID 33106495, 2020). "Recipients of Nod2−/−R161M CD4+ T cells developed more severe uveitis than those of R161M CD4+ T cells." (PMID 33106495, 2020). "Once established, the exacerbated uveitis mediated by Nod2−/− CD4+ T cells was characterized histopathologically by focal granulomatous inflammation, retinal folding, and vasculitis." (PMID 33106495, 2020). "IL-6 is involved in the differentiation of CD4+ T cells into Th17 cells known to play a pivotal role in uveitis." (PMID 33101305, 2020). "Clinical, histopathological and immunological features of EAU resemble multiple characteristics of human uveitis, such as increased breakdown of the blood-retinal barrier, immune cell infiltration, and the central importance of CD4+ effector T cells." (PMID 33106495, 2020).
uveitis (continued). "Reconstitution of lymphopenic hosts with Nod2−/− CD4+ T cells or retina-specific autoreactive CD4+ T cells lacking Nod2 reveals a T cell-autonomous, Rip2-independent mechanism for Nod2 in uveitis." (PMID 33106495, 2020). "From FACS analysis, human iPS-RPE cells suppressed uveitis T cells (proliferation of CD4+ T cells) from the PBMC of patients with Vogt-Koyanagi-Harada (VKH) disease." (PMID 32899567, 2020). "We therefore assayed for the abundance of PD-1+FoxP3+CD25+CD4+ Tregs cells in PBMCs of uveitis patients and healthy controls and determined if stimulation of the melanocortin-adenosinergic pathway induced Tregs." (PMID 31729418, 2019). "CD4+ T cell mediated uveitis is conventionally treated with systemic immunosuppressive agents, including corticosteroids and biologics targeting key inflammatory cytokines." (PMID 31475011, 2019). "In particular, IL-6 is involved in differentiation of CD-4 cells into Th-17 cells that have been shown to play a significant role in various immune-mediated diseases such as uveitis." (PMID 31523783, 2019). "In line with this, we observed an increase of (CCR6+CXCR3−) Th17 cells within CD4 TM cells that was noticeable for all uveitis types." (PMID 30429855, 2018). "Increased intracellular IL-10 and IL-17A and decreased intracellular IFNγ levels were found in CD4+ T-cells from active uveitis, 6 months after starting treatment, when the disease had clinically resolved." (PMID 29774027, 2018). "Within the CD4+ TM subset, uveitis patients showed a significant increase in the proportion of CCR6+CXCR3− cells (Th17) and a decreased proportion of CCR6−CXCR3+ (Th1) cells (p = 0.02 and p = 0.04 respectively)." (PMID 30429855, 2018). "Another study compared Treg levels in active and inactive uveitis patients and found that patients in remission on treatment (n = 25) had significantly increased levels of CD4+CD25+FoxP3+ Treg compared with active patients on treatment (n = 6)." (PMID 29774027, 2018). "Within the (CD3+) T cell populations, the ratio of CD4+ to CD8+ T cells was higher in uveitis patients (ratio [range] = 2.5 [1.4–9.4] vs. 1.5 [1.1–3.3], p = 0.03), due to a reduction in CD8+ cells in the CD3+ population." (PMID 30429855, 2018). "In animal models of experimental autoimmune uveoretinitis, a transfer of CD4+CD25highFoxp3+ Treg cells confer protection from uveitis induced by the uveitogenic retinal antigen IRBP." (PMID 26438050, 2016). "When CD4+ T cells from the uveitis patients were stimulated with IRBP1-20, the production of IL-22 definitely increased." (PMID 27166675, 2016). "The lower percentage of CD4+Foxp3+ T cells was observed in patients with active uveitis compared to inactive." (PMID 26438050, 2016). "The second model was experimental autoimmune uveoretinitis, an antigen-dependent CD4+ T-cell-initiated ocular autoimmune disease, which shares features with human uveitis." (PMID 26398933, 2015). "In BD patients with active uveitis, IL-17 levels are elevated in peripheral blood or ocular fluid, and it has been established that CD4+CD45RO+ (memory) T cells and γδ T cells are major sources of IL-17." (PMID 25061613, 2014). "In rodent models of uveitis, immunisation with whole proteins or peptides induces a CD4+ T cell-dependent uveitis." (PMID 24858699, 2014). "When CD4+ T cells were purified from the retinas of animals with uveitis that was induced by peripheral immunisation, and then studied ex vivo, both Th1 and Th17 cells were found." (PMID 24858699, 2014). "Although CD4+ T cell-driven disease is the dominant paradigm in models of uveitis, studies have shown that it is possible to induce autoimmunity within the eye using antigen-specific CD8+ T cells." (PMID 24858699, 2014). "The present study showed that IL-22 production by activated PBMCs and CD4+T cells was markedly increased in BD patients with active uveitis as compared to controls." (PMID 23527071, 2013).
uveitis (continued). "These experiments also showed that the frequency of IL-22 -positive CD4+ T cells was significantly higher in BD patients with active uveitis." (PMID 23527071, 2013). "An increased frequency of IL-22-producing CD4+T cells was also found in BD patients with active uveitis." (PMID 23527071, 2013). "The results showed a significantly elevated IL-22 production by activated CD4+ T cells in BD patients with active uveitis." (PMID 23527071, 2013). "Cluster of differentiation 4 (CD4)+ T cells from BD patients with active uveitis were co-cultured with anti-cluster of differentiation 3/cluster of differentiation 28 (CD3/CD28) antibodies in the presence of infliximab." (PMID 22546542, 2012). "As shown in the current experiments, infliximab significantly suppressed IFN-γ, IL-6 and IL-17 inflammatory cytokines in addition to TNF-α produced by activated CD4+ T cells from BD patients who have active uveitis." (PMID 22546542, 2012). "Autoreactive effector CD4+ T cells play a crucial role in the pathogenesis of autoimmune and autoinflammatory uveitis." (PMID 22685550, 2012). "CD4+ T cells from BD patients with active uveitis were co-cultured with rIL-2, anti-human CD3 Ab, and anti-human CD28 Ab in the presence of infliximab for 48 hours." (PMID 22546542, 2012). "Although IL-17 was undetectable in the serum of all subjects in the present study, a previous study found that IL-17 production by CD4+ T cells increased significantly in the presence of IL-23 in BD patients with active uveitis." (PMID 21655356, 2011). "Their visions were 20/32, 20/40, 20/40, respectively, and average CD4+ T lymphocyte count was 112 cells/μl while vitritis and uveitis were observed." (PMID 22115120, 2011). "The effect of anti-TNF-α treatment in uveitis is explained by increasing the fraction of peripheral CD4+ T cells expressing IL-10 with a recovery of visual function." (PMID 21180427, 2010). "Th17 cells, the IL-17 producing CD4+ T helper cells, are formed by heterogeneous subsets with different regulations and functions and have gained significant attention due to their crucial role in immune-mediated diseases, including uveitis." (PMID 40072803, 2025). "Many patients with undifferentiated uveitis, and in particular those with dense cellular aggregates on the inner corneal surface referred to as granulomatous-appearing keratic precipitates (KP), had very high proportions of CD4 T cells (50–64%)." (PMID 40060903, 2025). "In accordance, immunologic assessment of syndrome-associated uveitis forms, such as VKH disease, revealed the activation of CD4+ T lymphocyte-mediated cellular immunity and the infiltration of B lymphocytes and plasma cells into the vitreous, suggesting the participation of humoral immunity." (PMID 40270958, 2025). "However, there were 256 distinct TCR clonotypes out of 416 TCR in P2+CD4+ T cells from the LN of AireGW/+Lyn−/− mice with uveitis, which were obtained in two independent experiments." (PMID 38261611, 2024). "Nevertheless, direct T-cell involvement has not been demonstrated in JIA-associated uveitis so far, despite the fact that CD4+ involvement is critical in the pathogenesis of JIA and experimental uveitis." (PMID 36979992, 2023). "Thus, a feature of cellular immunity in groups with complicated uveitis and syndromes was a higher level of CD4 helper lymphocytes and a lower level of CD8 suppressor lymphocytes, which reflected higher values of the immunoregulatory index." (PMID 37089809, 2023). "Together, these data show that in eyes with uveitis the majority of CD4+, and to a lesser extent CD8+, T cells express the costimulatory receptors CD28 and ICOS, and treatment with acazicolcept provides significant blockade of these receptors on ocular infiltrating T cells." (PMID 36976157, 2023).